ELANE (elastase, neutrophil expressed)
Diseases named in the same sentence as ELANE in open-access papers (continued):
Sharing a sentence is not in itself a finding about the gene and the disease.
neutropenia (54 papers, 2011 to 2026). "Diagnosis requires both cyclic neutropenia documented by serial monitoring and pathogenic ELANE variant confirmation." (PMID 42058194, 2026). "The disease and gene most frequently seen in this cohort is neutropenia, caused by alterations in ELANE, in six patients." (PMID 41190063, 2025). "In our group of neutropenia patients associated with ELANE alterations, the most frequent clinical manifestation was infections, and all patients had at least one elevated Ig class." (PMID 41190063, 2025). "The most common disease was neutropenia due to monoallelic variants in ELANE, in six patients, followed by X-linked agammaglobulinemia in four patients, and X-linked chronic granulomatous disease in three." (PMID 41190063, 2025). "In our patients with neutropenia associated with variants in ELANE, all variants, except one, occurred in exons four and five." (PMID 41190063, 2025). "We also demonstrated that missense mutations in exon 3 of ELANE induce neutropenia that can be ameliorated by G-CSF through alternative activation of CEBPB-dependent granulopoiesis, as shown in primary myelopoiesis from patients." (PMID 39560992, 2024). "ELANE-induced neutropenia is associated with dysfunction of the theisprotease enzyme rather than due to NE deficiency." (PMID 39300084, 2024). "Results of this study provide encouraging data to support the development of NE inhibitors to treat ELANE-associated neutropenia." (PMID 39867870, 2024). "The sample size was limited, and there is a great diversity of the mutations causing ELANE associated neutropenia." (PMID 39867870, 2024). "This potential clearly differs from the differentiation arrest at the promyelocyte stage in severe neutropenia by ELANE mutations." (PMID 38238087, 2024). "It has been reported that mutations in the ELANE gene are found in 80–100% of cyclic neutropenia (CN) cases and 35–63% of severe neutropenia (SCN) cases." (PMID 37118811, 2023). "ELANE mutations lead to neutropenia, which plays an important role in innate immunity, weakening anti-bacterial ability and effect in coagulation, angiogenesis, inflammation resolution and tissue repair." (PMID 37118811, 2023). "Neutropenia-associated ELANE mutations are usually frame shift and termination mutations that result in structural changes in protein." (PMID 37118811, 2023). "Autoimmune diseases with ELANE mutations associated with neutropenia can be cured through allogeneic hematopoietic stem cell transplantation." (PMID 37118811, 2023). "These specific amino acid substitutions were chosen based on clinical studies of ELANE associated neutropenia." (PMID 36052149, 2022). "We developed an HL60 cell model for ELANE neutropenia and previously demonstrated that transient and regulated expression of mutant ELANE causes cell death by accelerated apoptosis." (PMID 36052149, 2022). "ELANE associated neutropenia is an autosomal dominant disease and there is a functional normal NE product translated from the healthy allele." (PMID 36052149, 2022). "Based on observations in primary patient samples, studies mainly aimed at the role of the unfolded protein response (UPR) and increased apoptosis in ELANE-mutant myeloid progenitor cells as the cause of neutropenia." (PMID 34854832, 2022). "Another approach for genetic correction of ELANE associated neutropenia is the CRISPR/Cas9 mediated direct correction of ELANE mutations utilizing the cell’s homology directed repair (HDR) machinery." (PMID 36052149, 2022). "In this review, we sum up the studies exploring mechanisms of neutrophil deficiency, biological role of NE in neutrophil and the effects of ELANE mutation and neutropenia pathogenesis." (PMID 33968054, 2021). "ELANE mutation was first mentioned in the Horwitz report on neutrophil elastase as a cause for cyclic neutropenia, and the next year, the same team identified ELANE mutations in patients with SCN." (PMID 33968054, 2021).
neutropenia (continued). "It has been observed that many mutations in the gene for the primary granule protein neutrophil elastase (ELANE) cause neutropenia." (PMID 34572056, 2021). "Neutropenia is a disease that can be associated with mutations in one of the serine protease genes, ELANE." (PMID 33996745, 2021). "SCN1 patients with ELANE mutations suffer from neutropenia yet display eosinophilia in the bone marrow and blood, as revealed by smear examination but not by automatic blood analysers." (PMID 31176364, 2019). "SCN due to ELANE mutations causes persistent neutropenia, but surprisingly, ANC of the patient was occasionally elevated." (PMID 25705433, 2015). "CN is a rare autosomal dominantly inherited neutropenic disorder caused by a mutation of the ELANE gene located on chromosome locus 19p13.3, which encodes neutrophil elastase." (PMID 25880377, 2015). "Bone marrow examination showed mild or profound maturation arrest, as described for other congenital neutropenias such as those associated with the ELANE mutation." (PMID 23656970, 2013). "ELANE mutations were identified in 1999 by linkage analysis and positional cloning in 13 families with a long history of cyclic neutropenia with autosomal dominant transmission." (PMID 21595885, 2011). "By comparison with other forms of congenital neutropenia, neutropenia due to ELANE mutations is associated with the most severe infectious complications." (PMID 21595885, 2011). "The term Kostmann's syndrome is sometimes used, inappropriately, for neutropenia with ELANE mutations." (PMID 21595885, 2011). "Congenital neutropenia is often linked to mutations in genes such as ELANE, HAX1, and SBDS." (PMID 40418265, 2025). "In addition, rare causes of neonatal neutropenia include severe congenital neutropenia due to gene mutations, such as ELANE, HAX1, and G6PC3, as well as neonatal alloimmune neutropenia caused primarily by maternally derived anti-neutrophil antibodies." (PMID 40722810, 2025). "Cases with severe congenital neutropenia caused by the ELANE mutation." (PMID 41477439, 2025). "Cyclic neutropenia presents with similar symptoms of fever and mouth ulcers and can be distinguished by identifying the exact pattern of fever by keeping a fever diary, monitoring blood counts for neutropenia, and by genetic testing for mutations in the ELANE gene." (PMID 41425676, 2025). "Patients with heterozygous mutations in the ELANE gene might develop severe life-threatening congenital neutropenia, or cyclic neutropenia with mild to moderate clinical characteristics." (PMID 39300084, 2024). "Neutropenia is the main clinical manifestation of ELANE mutations." (PMID 37118811, 2023). "Neutropenia can be classified as congenital neutropenia and acquired neutropenia, dominant mutations of autosomal in ELANE gene is the most common reason of congenital neutropenia, and virus, therapeutic radiation, and drugs can all lead to acquired neutropenia." (PMID 37380948, 2023). "Dominant mutations of autosomal in ELANE gene is the most common reason of congenital neutropenia." (PMID 37380948, 2023). "Carriers of ELANE mutation suffered from pure neutropenia as a cause of immunodeficiency." (PMID 33968054, 2021). "SCN is most often caused by autosomal dominant mutations in ELANE, the gene encoding neutrophil elastase, but how these mutations give rise to severe neutropenia is still largely unknown." (PMID 33205068, 2020). "Congenital neutropenias due to mutations in ELANE, SBDS or HAX1 or in the setting of glycogen storage disease (GSD) which is caused by SLC37A4 mutation, often require prolonged granulocyte colony stimulating factor (G-CSF) therapy to prevent recurrent infections and hospital admission." (PMID 31788408, 2019). "The mechanism for how autosomal dominant mutations in ELANE induce neutropenia is still unclear." (PMID 25165726, 2014).
neutropenia (continued). "ELANE (neutrophil Elastase) mutations are the most frequent known cause of congenital neutropenia and are observed in two subtypes: congenital or permanent severe neutropenia, and cyclic neutropenia." (PMID 21595885, 2011). "In fact, G-CSF therapy attenuates ELANE mutation-caused neutropenia which might develop leukemia." (PMID 35768562, 2022). "ELANE mutations may trigger neutrophil precursors’ death and lead to neutropenia." (PMID 35391795, 2022). "In fact, though the ELANE mutation alone, unreported in the GnomAD database thus far, can explain the cyclic neutropenia of this patient, we cannot exclude that TNFRSF13B, present with a variant showing no homozygotes in the same database, may also be involved in the clinical phenotype." (PMID 34573280, 2021). "Of these, seven patients also had genetically determined neutropenia: five of them had defects of the ELANE gene, and the next two had changes in SRP72 (Pro257Arg) and TCIRG (Ala417Thr) genes." (PMID 41383606, 2025). "Mutations in ELANE, HAX1, GFI1, and SBDS can confirm the diagnosis of SCN, cyclic neutropenia, or SDS." (PMID 40418265, 2025). "We previously reported that cell-permeable neutrophil elastase (NE) inhibitors are a potential treatment for ELANE neutropenia, based on studies using HL-60 cells." (PMID 39867870, 2024). "This study, for the first time, suggests that in addition to neutropenia, the aberrant levels and functions of ELANE, SLPI and their downstream molecules in pulp cells play an important role in oral complications in SCN patients." (PMID 34580954, 2021). "Beyond ELANE, mutations in the haematopoietic cell-specific Lyn substrate (HCLS) 1-associated gene X1 (HAX1) were identified as a cause of neutropenia." (PMID 25764063, 2015). "More than 50% of patients with congenital severe neutropenia and nearly all patients with cyclic neutropenia harbour mutations in the ELANE gene encoding for the neutrophil elastase (NE), a broad-specificity serine protease localized in azurophil granules." (PMID 25165726, 2014). "Broadly, these conditions can be divided into those where neutropenia is the predominating feature, such as in ELANE, GFI1, HAX1, CSF3R and WAS mutations and those where neutropenia is part of a multi-system disorder." (PMID 23758768, 2013). "Defective packaging of cellular enzymes in granules (due to ELANE mutations) or cytoskeleton changes (WASP and dynamin 2 mutations) modify intracytoplasmic trafficking and result in neutropenia, possibly through an excess of apoptosis or defective maturation." (PMID 21595885, 2011). "Neutropenia is one of the symptoms of Wolcott-Rallison syndrome caused by mutations in PERK, encoded by the EIF2AK3 gene, and heightened ER stress was reported in neutropenias caused by mutations in ELANE and glucose-6-phosphate subunit α gene (G6PC3)." (PMID 39962231, 2025). "It has also been found than some patients with neutropenia have somatic variants in ELANE, as opposed to germline alterations." (PMID 41190063, 2025). "Cyclic Neutropenia: The ELANE gene is characterised by periodic drops in neutrophil counts." (PMID 40822568, 2024). "The previous series of patient’s laboratory tests were evaluated, which clearly showed the presence of cyclic neutropenia, with a 21-day turnover frequency, but additional tests, such as the detention of ELANE mutation, were not performed." (PMID 37834967, 2023). "Without family histories of neutropenia in Patient 3 and no ELANE mutations identified in parents of Patient 4, sporadic mutations, commonly reported in ELANE gene mutation, were suspected in both patients." (PMID 37993852, 2023). "A common genetic disorder of neutropenia is the ELANE or ELA2, which encodes neutrophil elastase." (PMID 37993852, 2023). "ELANE mutations can be associated with a variety of immunodeficiency diseases such as severe congenital neutropenia (SCN) and cyclic neutropenia (CN), which are two main clinical phenotypes related to neutropenia." (PMID 37118811, 2023).
neutropenia (continued). "The 4 patients with ELANE mutations showed permanent neutropenia with early-stage maturation arrest and no extra-hematopoietic manifestations." (PMID 35525891, 2022). "Although multiple mechanisms causing neutropenia have been postulated, none of these have so far been firmly linked to specific ELANE mutations [14▪]." (PMID 34854832, 2022). "Recent studies have shown that ELANE whole gene deletion mutation does not cause neutropenia in humans and mice." (PMID 33968054, 2021). "Heterozygous mutations identified in ELANE gene result in a SCN, which might be a life threatening condition, or a cyclic neutropenia (CyN) with moderate to mild clinical features." (PMID 33968054, 2021). "According to clinical data collected from the Severe Chronic Neutropenia International Registry, some patients carrying ELANE mutations can show cyclic neutropenia with a low risk of evolution to AML, whereas other patients exhibit severe neutropenia with high risk of AML." (PMID 32630050, 2020). "Studies of patients with ELANE mutations show that the main risk factor for leukemic onset is the severity of neutropenia and not the nature of the ELANE mutation." (PMID 21595885, 2011). "As p22-phox, ELANE, and cathepsin G are primarily expressed in granulocytes, analyses of these proteins may also be useful in identifying patients with other diseases that are accompanied by neutropenia." (PMID 39453496, 2024). "Molecular docking studies showed that MK0339 binds to an alternative site on the NE protein compared to other inhibitors with greater inhibitor-NE protein stability, suggesting a unique mechanism of action and supporting further investigation of MK0339 as a therapy for ELANE associated neutropenia." (PMID 39867870, 2024). "In addition to neutropenia that leads to oral infection, we show that severely downregulated neutrophil activity and ELANE and SLPI expression in dental cells could be involved in orodental infections." (PMID 34580954, 2021). "However, it is notable that whole deletions of ELANE do not cause neutropenia like single-point mutations, hinting at a role for intron retention." (PMID 34572056, 2021). "However, Elane mutations equivalent to those found in SCN patients do not cause neutropenia in murine models, precluding the possibility to analyze the additional effect of ELANE mutations in murine models." (PMID 33205068, 2020). "However, we cannot exclude the possibility that patient RT was a sporadic case of ELANE mutation and did not additionally harbor any other untested/unidentified neutropenia mutation and that his parents were carriers of this mutation." (PMID 30040071, 2018). "However, pathogenic ELANE mutations are distributed throughout NE, and at least some ELANE mutants retain NE activity, indicating that neutropenia is not a result of impaired NE proteolytic function." (PMID 27446090, 2016). "Among several associated genetic mutations, heterogeneous mutations of the ELANE gene coding for neutrophil elastase (NE) have been associated with both SCN and cyclic neutropenia (CN), and it is known to be correlated with more severe neutropenia and serious clinical manifestation in SCN." (PMID 25705433, 2015). "Therefore, G6PC3 mutation analysis should be considered in all cases of congenital, unexplained neutropenia, regardless of the presence of extra-hematopoietic manifestations or of parental consanguinity, once ELANE and HAX1 mutations are ruled out." (PMID 25391451, 2014). "We conclude that an orally absorbed, cell permeable inhibitor of neutrophil elastase, if proven safe and effective in a clinical trial, is a good alternative to G-CSF or gene editing to treat ELANE neutropenia." (PMID 36052149, 2022). "In contrast, the mutation downstream of the 50th nucleotide position within a late exon (4th and 5th) of ELANE avoids NMD, thus, produces defective NE that impairs neutrophil maturation and manifests as severe neutropenia." (PMID 33968054, 2021).
neutropenia (continued). "The entire ELANE deletions are not described in the context of neutropenia, and the few cases such as chromosome 19p terminal deletion including this gene phenotypically do not show neutrophil count deficiency." (PMID 33968054, 2021). "ELANE-induced neutropenia is not related to a NE deficit itself, but rather to a dysfunction of theisprotease." (PMID 33968054, 2021). "Mutations in ELANE can either cause severe congenital neutropenia (SCN), or, depending on the type of mutation, also cyclic neutropenia where phases of reduced neutrophil counts alternate with normal blood counts." (PMID 27942017, 2016). "However, an orally absorbed, cell permeable inhibitor of neutrophil elastase, if proven safe and effective in a clinical trial, might be the better alternative to G-CSF or gene editing to treat ELANE neutropenia." (PMID 36052149, 2022).